IL6 (interleukin 6)
Diseases named in the same sentence as IL6 in open-access papers (continued):
Sharing a sentence is not in itself a finding about the gene and the disease.
infection (continued). "In addition, the evolved strain (Evo) showed transiently increased virulence in a systemic mouse infection model, which correlated with increased organ-specific fungal burden and inflammatory response (TNFα and IL-6) in the brain." (PMID 25356907, 2014). "Phil82 IAV induced robust TNF and IL-6 production after 18 hrs of infection as previously reported." (PMID 24988208, 2014). "Finally, infection with KFDV P9605 also resulted in a significant induction of IL-6, IFN-γ, and MCP-1 in the spleen on day 2, while both KFDV P9605 and AHFV Zaki-1 induced significantly higher levels of IL-10." (PMID 24922308, 2014). "The authors also mentioned that the greater amount of TNF-α and IL-6 at the site of infection could overstimulate the recruitment of macrophages." (PMID 25538905, 2014). "However, at day 3 post-infection, the Socs4R108X/R108X mice showed significantly higher levels of cytokines and chemokines, such as IL-1β, IL-4, IL-5, IL-6, IL-12p40, IL-13, IFN-γ, and KC (CXCL1), MIP-2 (CXCL2) and MCP-1 (CCL2), respectively." (PMID 24809749, 2014). "Alternatively, the increases in CRP, and SAA could reflect the localized production of IL-6 in the liver, possibly as a site of infection, inflammation and/or tissue injury in the early acute Lyme phase." (PMID 24740099, 2014). "Moreover, weight loss in Trem1−/− mice was significantly attenuated and Trem1−/− mice further exhibited reduced levels of IL-6 in bronchoalveolar lavage fluid (BALF) at 10 days post infection." (PMID 24453980, 2014). "In this study, although the level of IL-6 in the middle ear was statistically lower in C5ar1−/− than WT mice, the high level of IL-6 on day 1 post Spn infection in the coinfection cohort might be attributed to the modulation of C5L2." (PMID 24740152, 2014). "Inflammation is a natural bodily response to damage or infection that is generally mediated by proinflammatory cytokines such as interleukin 1 beta (IL-1β), interleukin 6 (IL-6), and tumour necrosis factor alpha (TNFα), in addition to lipidic mediators such as prostaglandins and leukotrienes." (PMID 24772353, 2014). "The secretion of IL-6 might relate to high numbers of macrophages and neutrophils in the early infection." (PMID 24666970, 2014). "In our experiments, we observed an increased transcription of SAA at day 5 post-infection in response to VHSV that might be a consequence of the up-regulated IL-6 transcription detected from the second day of infection." (PMID 25338079, 2014). "In contrast, the older sibling with IRAK-4 deficiency demonstrated raised levels of CRP (192 mg/l; normal < 5 mg/l) and IL-6 (1983 pg/ml; normal < 7 pg/ml), potentially indicating a prolonged infection, a disease course which has also been reported in other IRAK-4-deficient patients with severe IPD." (PMID 24625087, 2014). "Infection induced a significant IL-6 and IL-10 secretion that peaked at 72 hours." (PMID 24489729, 2014). "Six days following C. jejuni infection hepatic IFN-γ, TNF-α, and IL-6 concentrations increased (p < 0.05−0.0001), but to even higher levels upon ΔhtrA knockout mutant as compared to parental C. jejuni WT strain infection (p < 0.05)." (PMID 24959425, 2014). "Since activation of nfkbiz and il6 is not attenuated after infection with a PorB-deficient MC58 strain, signal transduction initiated by TLR2/TLR1 does not seem to play a major role in HIBCPP cells, at least for stimulation of the IκBζ-IL6 axis." (PMID 25347003, 2014). "Selective loss of IL-6 without decrease in TGF-β as seen following BCG-TB1860 infection of BMDC would therefore polarize precursors to differentiate into Treg at the expense of TH17." (PMID 24945624, 2014). "The earliest increased cytokine was IL-6, which increased at day 2 post-infection." (PMID 24666970, 2014). "However, a strong correlation between elevation of IL-6 and IL-10 and severe pH1N1 infection was noted." (PMID 25003343, 2014).
infection (continued). "BCG-TB1860His infection also resulted in similar reduction of IL-2, IL-6, IL-12p40 and TNF-α." (PMID 24945624, 2014). "Potentially, differences in IL-6 levels could develop later in infection, but as the Δlgt strain cannot maintain long-term infection in mouse models, it was not feasible to investigate this." (PMID 25172490, 2014). "Here, we opted to focus on IL-6, a cytokine that can directly affect macrophages, exert a variety of pro-inflammatory effects, and which is produced along with IL-4+IL-13 following infection with helminth parasites." (PMID 24736635, 2014). "IL-6 concentrations are proportional to the severity of infection." (PMID 24852692, 2014). "IL-6 levels remain elevated and only return to normal levels months after infection and treatment." (PMID 24740099, 2014). "In vitro infection of BMDM also showed a hyporesponsive IL-6 phenotype in Ity3.RecG mice." (PMID 24505352, 2014). "Interestingly, blocking of TLR4 before infection decreased epithelial IL-6 secretion, but increased the CREB-activated IL-10 production." (PMID 24489729, 2014). "Additionally, serum levels of IL-6 from ΔspxA1 and ΔspxA2-infected mice returned to basal levels at 9 h post-infection, approximately three hours earlier than the WT-infected mice." (PMID 25264876, 2014). "Besides, Serum levels of TNF-α and IL-6 in mice infected with mutant strains return to basal levels at 9 h post infection, more quickly than in WT-infected mice." (PMID 25264876, 2014). "1,25(OH)2D3-VDR may exhibits its anti-inflammatory properties in MRSA-stimulated infection by inhibiting nuclear translocation of NF-kB-p65 and transcripts of IL-8, IL-6, TNFα, and NR4A2 in hMSCs." (PMID 24661536, 2014). "The initial peak of IL-6 as early as 2 days post-infection may be related to the early activation of the acute phase protein genes in the hepatocytes, disclosed by previous microarray studies." (PMID 24637903, 2014). "On the other hand, TNFα mRNA increased 200-fold after infection with U112, and TNFα and IL-6 levels in the culture medium were up to 30-fold higher than we observed for LVS and Schu S4, confirming that F. novicida is significantly more proinflammatory than F. tularensis." (PMID 25295729, 2014). "In contrast, cytokines generally induced in the later stage of acute pathogenic infection, such as IL-6, IL-18 and TNF-α, were less or not increased, suggesting an early control of IA." (PMID 24991927, 2014). "Infection increased secretion of cytokines/mediators IL-1RA, IL-6, TNF-α and TIMP-1." (PMID 24416445, 2014). "IL-6 is a cytokine of the early host response to infection, preceding the increase of CRP." (PMID 25485809, 2014). "The expression of IFN-γ and IL-6 in bursa tissue of chicken infected with the infectious bursal disease virus (IBDV) did not increase in CLA-fed birds as much as in control animals 3 days post infection." (PMID 23857174, 2013). "The correlation coefficients (R2) for TNF-α, IL-1β, IL-6 and IL-12 with percent apoptosis were 0.906, 0.864, 0.879 and 0.890 respectively (P<0.05) on 5th day and 0.830, 0.669, 0.639 and 0.846 respectively (P<0.05) on 6th day of infection." (PMID 23667550, 2013). "Since IL-6 mediated, at least in part, the inhibition of TNF and IL-12 secretion by SOCS3-deficient BMM and BMDC, the role of IL-6 in the susceptibility of gp130F/F mice to infection with M. tuberculosis was studied." (PMID 23853585, 2013). "Indeed, when similar infectious doses are applied, although infection with virulent Kp52.145 is lethal, the cytokines IL-1β, IL-6, and IL-17 and the chemokines CCL2, CCL3 and CCL4 are produced in similar manner." (PMID 23554169, 2013). "The results showed that among these markers, interleukin 6 had the greatest predictive value for determining ill newborns (case group) and predicting mortality rate, while IL-8 was more valuable for diagnosing definitive infection." (PMID 24570828, 2013).
infection (continued). "At 2 weeks post-infection (n = 3), both KrasG12D and KrasG12D; IL-6-/- mice had early lung lesions." (PMID 24260500, 2013). "IL-6, which acts as both a pro-inflammatory and anti-inflammatory cytokine, and is secreted by T-cells and macrophages to stimulate an immune response during infection and after tissue trauma was also investigated as a marker of immune response." (PMID 23343139, 2013). "At 2 days after infection, the levels of IL-1, IL-6, TNF-α, and IL-10 were reduced; at 14 days after infection, the levels of IL-1, KC, TNF-α, and IFN-γ were reduced, and a reduction in the IL-6, KC, and IL-10 concentrations was observed at 28 days after infection." (PMID 23818746, 2013). "The infection may lead to activation of monocyte/macrophage lineage and expression of interleukin-6 (IL-6), interleukin-10 (IL-10), and tumour necrosis factor-alpha (TNF-α) the serum levels of which have been correlated with the severity of the infection." (PMID 23983770, 2013). "However, in these considerations the time-course of events should be taken into account, since IL-6 participates also in processes that arrest the inflammatory response to infection and tissue injury and ensure a good restoration of the affected area." (PMID 24489578, 2013). "TNF-α, however, is just one of the cytokines released in response to L. monocytogenes with other pro-inflammatory cytokines, including IL-6 and IL-1β, released during infection in vivo, and mast cells have been shown to secrete these in response to L. monocytogenes in vitro." (PMID 23460827, 2013). "The increase in kidney bacterial load together with iron deposition following infection clearly induced a local inflammatory response that is reflected by higher expression of renal Il1 and Il6 mRNA levels by a factor of 2.5 fold compared to wild-type controls." (PMID 23390527, 2013). "In addition, infection of BoMac cells with the bovine isolate resulted in a significant upregulation of the anti-inflammatory cytokines IL-6 and TGF-β1 at 24 h p.i., when compared with cells infected with the ovine isolate." (PMID 23509800, 2013). "Of the 23 analytes measured in this study, all but 6 (IFNγ, IP-10, MIG, MCP-1, IL-17 and IL-6) showed no discernible association with 4–9 weeks infection or with chemotherapy." (PMID 23469125, 2013). "However, infection with MVA or NYVAC induced the expression of IL-6, TNF-α and IL-10, being this induction higher in KO mice." (PMID 24244156, 2013). "It is known that IL-6, is a pleiotropic cytokine that is produced by a number of cell types including macrophages, endothelial cells, B cells and mast cells, plays a crtical role in the host response to infection and inflammation." (PMID 23637741, 2013). "In addition the reduced lung levels of IL-6, IL-1β as well as neutrophil influx upon infection under Panobacumab treatment would indicate that the reduction of the bacterial load by Panobacumab resulted in an overall attenuated pro-inflammatory response." (PMID 24023870, 2013). "This relationship may involve the pivotal action of IL-6 in the recovery phase of infection, which favours the switch from innate to adaptive immunity leading to B cell expansion and IgG3 production." (PMID 23302155, 2013). "The reductions in TNF-α and IL-6 by AF-08 were prominent early in the infection, suggesting that the beneficial effect of AF-08 was due to the suppression of inflammation early after infection." (PMID 24250719, 2013). "Moreover, laser capture microdissection (LCM) confirmed that most of the IL-6 expression was produced by epithelial cells after 6 months of infection." (PMID 23520544, 2013). "Infection of either WT or K21 MEFs led to an induction of IL-6 production." (PMID 23596308, 2013).
infection (continued). "When WT mice were infected with S. aureus, IL-6 release was detected in the livers at 6 h post-infection and continued to gradually increase for at least until 5 d post-infection; it also appeared in the blood and peaked at 3 d post-infection." (PMID 24058538, 2013). "Early infection cytokines interleukin 6 (IL-6) and tumor necrosis factor (TNF), which are both secreted by macrophages, showed a statistically significant increase (P <0.05 by Student’s t-test) in the bgh lung as early as day 1, indicating the onset of an inflammatory response." (PMID 24360193, 2013). "Overall, st2−/− mice tended to have higher mediator levels in lungs than WT mice; especially 14 days after infection with influenza A modest but statistically significant differences were seen in pulmonary IL-6 (P<0.001), IL-1β (P<0.01), KC (P<0.05), IL-10 (P<0.05) and IL-33 (P<0.05) concentrations." (PMID 23483993, 2013). "Tumor necrosis factor (TNF-α) and interleukin-6 (IL-6) are pro-inflammatory cytokines, and while TNF-α activates innate responses to infection and promotes an anti-viral state in cells, IL-6 has been described as one of the mediator coordinating the interface between adaptive and innate immunity." (PMID 23457480, 2013). "Similarly, gp130F/F BMM expressed lower IL-6 protein and mRNA levels after infection with either M. tuberculosis or BCG, or stimulation with Pam3CSK4." (PMID 23853585, 2013). "To determine what cytokines might be promoting the increased IL-17 responses in IL10SD mice, we looked at gene expression of IL-6, IL-23, TGFβ1 and IL-1β 1 week after infection of control and IL10SD mice." (PMID 23555256, 2013). "At 4 weeks post-infection, KrasG12D; IL-6-/- mice had more early lung lesions than KrasG12D mice." (PMID 24260500, 2013). "Moreover, F9/10 possessed the ability of inducing high expression of IL6 on the long term of infection." (PMID 23758678, 2013). "However, in WT cells, preincubation of MAV-1 with antiserum resulted in a significant increase in IL-6 production over and above that generated by infection with MAV-1 alone." (PMID 23596308, 2013). "However, before the start of treatment (6 weeks after infection) IL-17 and IL-6 levels were below 2.2 pg/ml (or undetectable) in all samples." (PMID 23469125, 2013). "On the other hand, Nlrp3−/− macrophages slightly altered IL-6 levels after infection with the L.p." (PMID 24058709, 2013). "Augmented IL-6 elaboration can occur during various infections or inflammation." (PMID 24455461, 2013). "Of the cytokines/chemokines studied only IFNγ, IP-10, MIG, MCP-1, IL-17 and IL-6 showed measurable shifts in concentration that could be related to infection and or treatment." (PMID 23469125, 2013). "Since in BF IL-1 is not increased and IL-6 is very high during the first two weeks of infection, IL-6 could play a role with IFN-γ in active synthesis of factor B in the liver." (PMID 21912565, 2012). "Infection with respiratory viruses, such as RV and RS virus activates these cells via the activation of TLRs, and induces mucus production and the secretion of various pro-inflammatory cytokines and monokines, including IL-6, IL-8, and RANTES." (PMID 22966430, 2012). "Repeated infections with T. regenti evoke dominant production of Th2-type cytokines, and the first and most abundant cytokine detected in supernatants of skin biopsies from mice after repeated infections is IL-6, which can initiate Th2-type polarization via induction of IL-4." (PMID 23125918, 2012). "IL-6 has been implicated in both avian influenza A H5N1- and SARS-induced cytokine storms, and from our data in humans we hypothesized that IL-6 would have a similar damaging role during severe H1N1pdm infection." (PMID 22679491, 2012). "IL-6 was found to be highly up-regulated in the same animals 14–18 h after experimental infection." (PMID 22953717, 2012).
infection (continued). "However, it is plausible that by day 16 there was so much infection in C57BL/6 lungs that IL-6 and TNF-α levels increased so that they were more highly expressed in C57BL/6." (PMID 23006927, 2012). "Additionally, we observed that ClpV contributes to IL-1β, IL-6, IL-10, and IL-17 production in murine macrophages in vitro, and using natural host infection, confirmed that changes in IL-17 and IL-6 production in vivo are ClpV-dependent." (PMID 23071529, 2012). "In acute BF, high IL-6 levels could be due to synthesis at sites of infection by activated and damaged ECs, infiltrating monocytes, and TH2 T cells." (PMID 21912565, 2012). "A similar difference was observed in the case of IL6 at 24 h post infection (P 0.0176)." (PMID 22672588, 2012). "Nevertheless, production of several chemokines, including Rantes, Mip1-α and IL-8, and such cytokines as interferon (IFN) α and β, Tnf-α and IL-6 has been observed upon infection of a wide variety of established and primary human and murine cells in culture and in vivo." (PMID 22912576, 2012). "Taken together, the data suggests that miR-H6 targeting of ICP4 inhibits HSV-1 productive infection and decreases interleukin 6 production in HCE, and this may provide an approach to prevent HSV-1 lytic infection and inhibit corneal inflammation." (PMID 22550533, 2012). "Also, the levels of inflammatory cytokine IL-6 was found to be lower in the GP treated group compared to the untreated control after lethal infection." (PMID 22442708, 2012). "IL-6 and IL-8 are considered as the major pro-inflammatory cytokine and chemokine for the recruitment and activation of neutrophils and macrophages at the site of infection." (PMID 22248145, 2012). "In contrast, the expression of other regulatory cytokines such as IL2, IL6 and IL17a (not shown) were not significantly different in resistant and susceptible contexts, nor affected by infection." (PMID 22720048, 2012). "Thus, for direct comparisons to the brain, we determined the levels of virus replication and expression of IFNβ, MxA (IFNβ-induced gene) and IL-6 mRNA during acute and early infection in the spleen by quantitative real-time PCR (RT-PCR)." (PMID 22952612, 2012). "The objective of the present study was to determine whether there was an association between polymorphisms of TNF, LTA, IL1B, IL6, IL8, and CCL1 and the infection and severity of the illness caused by the pandemic A/H1N1 in Mexico in 2009." (PMID 23148654, 2012). "However, while IFN-γ and IL-6 were present at similar concentrations compared with control mice at days 14 and 21 post infection, IL-12p40 was significantly increased at day 21 in pDC-depleted animals." (PMID 23119083, 2012). "We sought to investigate the role of inflammatory mediator IL-6 in severe H1N1pdm infection." (PMID 22679491, 2012). "We observed increased IL-6 levels in response to severe H1N1pdm infection in mice." (PMID 22679491, 2012). "IL-6 mobilizes and amplifies both local and systemic innate immune defenses against infection." (PMID 23056598, 2012). "The CSF IL-6 concentration was increased above control levels in both early and late stage cases, there was also significant correlation to duration of infection (rs = 0.46 p<0.01)." (PMID 23145191, 2012). "We next evaluated Il6 gene regulation at the mRNA level following H1N1pdm infection." (PMID 22679491, 2012). "Here, we investigated the role of IL-6 in severe H1N1pdm infection." (PMID 22679491, 2012). "In this malarial model, all the pro-inflammatory cytokines, TNFα, IFNγ, IL-1, IL-6 and IL-18 and the anti-inflammatory cytokine IL-10, were significantly elevated in the plasma throughout the infection with the highest level recorded during the late critical stage." (PMID 23323093, 2012).